MYCN (MYCN proto-oncogene, bHLH transcription factor)
Diseases named in the same sentence as MYCN in open-access papers (continued):
Sharing a sentence is not in itself a finding about the gene and the disease.
neuroblastoma (continued). "Since their expression levels are so low, further depletion of their expressions in neuroblastoma cells would not have a dramatic effect on its target gene (MYCN) expression." (PMID 27764804, 2016). "High expression of PMAIP1 in the subset of MYCN-amplified neuroblastomas was confirmed in a second dataset of neuroblastomas, again without differential expression of other key BCL-2 family members." (PMID 26859456, 2016). "Primary neuroblastomas lacking MYCN amplifications displayed differential CD9 promoter methylation in methyl-CpG-binding domain sequencing analyses, and high-level methylation was associated with advanced stage disease, supporting epigenetic regulation." (PMID 27572323, 2016). "Global analysis of 986 human neuroblastoma datasets revealed a negative correlation between hASH1 and neuron differentiation that was independent of the N-myc (MYCN) oncogene." (PMID 28066180, 2016). "Mechanisms involved include ER stress coupled to apoptosis dependent on phospholipase C activation in MYCN-amplified neuroblastoma cells and, irrespective of MYCN status, differentiation of surviving cells." (PMID 27242543, 2016). "Further, DpC displayed greater activity than Dp44mT in the remaining neuroblastoma cell lines without MYCN amplification (i.e., SK-N-AS and SH-SY5Y) in terms of both early and late apoptosis." (PMID 27678372, 2016). "Fourth, in multiple mouse models of MYCN-amplified neuroblastoma, complete and sustained regressions were noted, without any overt signs of toxicity to the mice." (PMID 26859456, 2016). "Likewise, SGO1 mRNA and protein levels were higher in MYCN-amplified neuroblastoma cell lines (IMR32, SK-N-BE, and NB39) than in a neuroblastoma cell line harboring a single copy of MYCN (SK-N-AS)." (PMID 27539729, 2016). "In addition, PF-06463922 is effective in vivo in both subcutaneous and orthotopic xenograft models of neuroblastoma, as well as the Th-ALKF1174L/MYCN-driven transgenic neuroblastoma mouse model." (PMID 27483357, 2016). "It was also of interest that Dp44mT demonstrated relatively higher efficacy against MYCN amplified cell lines relative to neuroblastoma cells without MYCN amplification." (PMID 27678372, 2016). "Chromosome rearrangements resulting in an increased activation of TERT (telomerase reverse transcriptase) have recently been identified in ~23% of high-stage neuroblastoma with very poor prognosis but no MYCN amplification." (PMID 28035989, 2016). "The comparative analysis of neuroblastoma tumors having or lacking amplification of the prognostic MYCN marker revealed that AhR expression was inversely correlated with MYCN amplification and, importantly, with an increased grade of tumor differentiation." (PMID 27243009, 2016). "In contrast to SGO1 knockdown, however, cohesin subunit knockdown did not significantly alter the cell-cycle profile, even in MYCN-overexpressing neuroblastoma cells." (PMID 27539729, 2016). "Overall, these results suggest that multiple differentiation-inducing miRNAs play roles in regulating the expression of MYCN in neuroblastoma cells regardless of the genetic backgrounds of the cell lines." (PMID 27764804, 2016). "It has been well-documented that neuroblastoma cells that lack amplified MYCN generally express MYC rather than MYCN." (PMID 28713571, 2016). "Therefore we examined the therapeutic effect of brigatinib as a single agent in BalbC/NUDE mice injected with human neuroblastoma CLB-BAR cells, (ALK Δ4-11 and MYCN amplified, ALK addicted) subcutaneously." (PMID 27049722, 2016). "All nine investigated neuroblastoma cell lines displayed active β-catenin, i.e. the dephosphorylated nuclear form, as well as the canonical Wnt target gene Axin2, regardless of MYCN gene amplification status." (PMID 27036398, 2016). "MiR-19a and 19b directly target N-Myc (MYCN), and could suppress the endogenous protein expression in a neuroblastoma cell line." (PMID 27708666, 2016).
neuroblastoma (continued). "Two human neuroblastoma cell lines (NGP: a MYCN-amplified line, and SH-SY5Y a MYCN non-amplified line) were implanted in the renal capsule of nude mice to establish the model." (PMID 27861510, 2016). "Overall, the results suggest that the differentiation-inducing functions of miR-506-3P and miR-449a are at least partially, if not completely, mediated by down-regulating MYCN expression in neuroblastoma cell lines." (PMID 27764804, 2016). "Immunohistochemistry for β-catenin revealed a general higher expression in SK-N-AS neuroblastoma tumors without amplification of MYCN as compared to MYCN-amplified SK-N-DZ tumors." (PMID 27323822, 2016). "To substantiate our in vitro and in vivo human xenograft findings, we found that the combination is effective in a MYCN-amplified neuroblastoma PDX model, which demonstrated only modest single-agent MLN8237 activity, mirroring clinical activity of MLN8237 in neuroblastoma." (PMID 26859456, 2016). "Next, to determine whether SGO1 affects proliferation of neuroblastoma cells, we knocked down SGO1 in MYCN-overexpressing SH-EP cells using short hairpin RNA (shRNA)." (PMID 27539729, 2016). "We showed that HDAC2 cooperates with MYCN to suppress apoptosis mediated by miR-183, and that HDAC3 interacts with MYCN to transcriptionally repress the GRHL1 transcription factor, which exerts tumor suppressive effects in neuroblastoma." (PMID 27572323, 2016). "Overall, DpC was the most active agent in inducing apoptosis in the 4 neuroblastoma cell lines and importantly demonstrated marked activity irrespective of MYCN amplification." (PMID 27678372, 2016). "In both MYCN-amplified and non-amplified neuroblastoma cell lines, treatment with INK128/MLN0128 suppressed cell proliferation." (PMID 26771642, 2016). "Although other factors have been described to modulate RA differentiation in neuroblastoma, hASH1 represents a unique target and a possible biomarker for all neuroblastoma, independent of MYCN amplification status." (PMID 28066180, 2016). "Amplification of MYCN oncogene has proven to be a major negative prognostic biomarker for neuroblastoma, an aggressive childhood cancer with overall survival of less than 50% for high-risk disease." (PMID 27571165, 2016). "This lack of success is primarily attributable to the MYCN oncogene, which regulates numerous aspects of neuroblastoma development and progression." (PMID 27531891, 2016). "About 15 % of the neuroblastoma cases show MYCN gene amplification, a genomic aberration used as a negative prognosis indicator." (PMID 26728659, 2016). "The relationship between MYCN and PMAIP1 expression in MYCN-amplified neuroblastoma cells was significant, raising the possibility that MYCN may regulate PMAIP1 in these tumors." (PMID 26859456, 2016). "Our findings in MYCN non-amplified neuroblastoma cell lines show that PGE2 enhances cell viability through the EP4 receptor, whereas this was attenuated by inhibition of PGE2 with specific COX-2 inhibitors." (PMID 25266063, 2015). "RA is used clinically to differentiate neuroblastoma but is not as effective for MNA tumours as MYCN single copy ones." (PMID 26673823, 2015). "This dataset includes a cohort of 102 neuroblastoma patients with metastatic tumors lacking MYCN amplification." (PMID 25351211, 2015).
neuroblastoma (continued). "Gain and loss of β-catenin function, PGE2, the adenylyl cyclase activator forskolin and pharmacological inhibition of cyclooxygenase-2 (COX-2) were studied in two human neuroblastoma cell lines without MYCN amplification." (PMID 25266063, 2015). "Knockout of MYCN protein by targeting with siRNA, or alternatively, destabilizing the protein using an inhibitor of the upstream PI3K signaling pathway, has been shown as an effective preclinical therapy for neuroblastoma." (PMID 26734566, 2015). "Recent developments in neuroblastoma genomics suggest that gain or amplification is not the only mechanism that affects MYCN function in paediatric tumours." (PMID 25749049, 2015). "Although important for the genesis of neuroblastoma, MYCN overexpression without gene amplification is often associated with good outcomes." (PMID 26673823, 2015). "Recent studies correlating microarray signals from MYC target genes with the clinical outcome of neuroblastoma found that MYC transcriptional signatures are predictive of disease outcome independent of MYCN amplification status." (PMID 25860940, 2015). "From these experiments, we conclude that in our hands, stable knockdown or overexpression of TRPM7 does not affect viability and proliferation of both MYCN-negative and MYCN-amplified neuroblastoma cell lines." (PMID 25797249, 2015). "We therefore repeated key experiments in a different human neuroblastoma cell line without MYCN amplification, SK-N-SH." (PMID 25266063, 2015). "As the MYCN 3′UTR-miRNA library screen was performed in HEK293T cells, we next aimed to specifically select miRNAs targeting MYCN in neuroblastoma cells by integrating the obtained screen results with miRNA expression data from primary neuroblastoma tumors." (PMID 25294817, 2015). "In neuroblastoma, it has been shown that β-catenin expression is increased in MYCN non-amplified neuroblastoma cell lines." (PMID 25266063, 2015). "Using small-molecule inhibitors, we now demonstrate that selective inhibition of HDAC8 exhibits antineuroblastoma activity without toxicity in two xenograft mouse models of MYCN oncogene-amplified neuroblastoma." (PMID 25695609, 2015). "In neuroblastoma, another embryonal tumor, in which amplification of MYC family genes is correlated with poor prognosis, targeting PI3K/mTOR resulted in down-regulation of MYCN expression." (PMID 25402633, 2015). "Accordingly, we used a unique, MYCN non-amplified mouse model of human high-risk aggressive metastatic neuroblastoma coupled with whole genome miRNA approach to investigate the functional reorganization of metastamiRs in NB progression." (PMID 26148557, 2015). "In this study, we focused on the contribution of PGE2 and β-catenin to progression of neuroblastomas without MYCN amplification." (PMID 25266063, 2015). "This analysis indicated that GATA3 is a prognostic marker in neuroblastoma, which is independent of the status of MYCN amplification." (PMID 25351211, 2015). "In brief, for each miRNA, mRNAs were ranked according to decreasing expression correlation in MYCN non-amplified neuroblastoma tumors." (PMID 25294817, 2015). "While the adrenal gland is a frequent site of neuroblastoma origin, the impact of MYCN expression on multipotent mammalian SAPs has not been described." (PMID 26222553, 2015). "The integration of the screen results with miRNA expression data from MYCN non-amplified primary neuroblastoma tumors further identified 5 MYCN-targeting miRNAs with positive correlation to MYCN expression or activity." (PMID 25294817, 2015). "Although exogenous c-Myc similarly activates this reporter in 293T cells, it is unlikely to contribute to GLS2 activation in MYCN-amplified neuroblastoma cells as these cells barely exhibit detec-Myc expression." (PMID 26528759, 2015).
neuroblastoma (continued). "To extend these studies to an in vivo mouse model, we established a new cell line that stably expressed the α4-GFP fusion protein in C1300 mouse neuroblastoma that lacked endogenous expression of integrin α4 and lack MYCN amplification." (PMID 25973900, 2015). "The MYCN gene is amplified or overexpressed in a number of pediatric cancers including both medulloblastoma and neuroblastoma and is a negative prognostic factor in both diseases." (PMID 26029667, 2015). "SH-EP2 is a non-neuronal (S-type) subclone of the SK-N-SH human neuroblastoma cell line with no expression of MYCN." (PMID 25797249, 2015). "We observed that the compounds inhibited the growth of both MYCN positive and negative neuroblastoma cells." (PMID 25477524, 2015). "In support of this notion, we previously demonstrated that, unlike hepatocellular carcinoma cells, MYCN-amplified neuroblastomas strictly rely on large amounts of exogenous glutamine for cell survival." (PMID 26528759, 2015). "More importantly, MYCN expression does not correlate with the prognosis of adverse outcome in advanced-stage neuroblastoma with non-amplified MYCN." (PMID 26148557, 2015). "Of further notice, 17 out of 29 identified MYCN-targeting miRNAs were considered not to be relevant for MYCN regulation in the context of neuroblastoma, due to lack of inverse correlation to MYCN expression or activity, or due to unavailable expression data." (PMID 25294817, 2015). "Similarly in human neuroblastoma, JQ1 targeted BRD4 to regulate MYCN expression, and induced cell death." (PMID 25849938, 2015). "We were only interested in cases without MYCN amplification as it has previously been reported that β-catenin expression is increased in neuroblastoma tumours and cell lines without amplification of MYCN." (PMID 25266063, 2015). "In summary, 12 of 29 MYCN-targeting miRNAs were inversely correlated to either MYCN expression or MYCN activity in MYCN non-amplified tumor samples, and therefore likely regulate MYCN in neuroblastoma." (PMID 25294817, 2015). "In conclusion, we identify 12 MYCN-targeting miRNAs in with regulatory effects on MYCN expression levels or activity in MYCN non-amplified neuroblastoma." (PMID 25294817, 2015). "Regarding neuroblastoma, β-catenin expression is increased in MYCN non-amplified neuroblastoma cell lines and β-catenin target gene transcription is increased in neuroblastoma tumours without MYCN amplification." (PMID 25266063, 2015). "To see if and how TRPM7 affects viability and proliferation of MYCN-negative and positive neuroblastoma cells, we generated stable TRPM7 knockdown SH-EP2 and SH-SY5Y cells using a previously characterized lentiviral shRNA construct." (PMID 25797249, 2015). "Several studies focused on the up-regulation of apoptosis in neuroblastoma cells by down regulation of the PI3K/AKT pathway and found that cells with MYCN amplification show a greater inhibition of the PI3K/AKT pathway which is considered to be a major factor for the prognosis of neuroblastoma." (PMID 26010602, 2015). "Recently, XAV939 has been shown to decrease neuroblastoma cell survival by inhibiting β-catenin transcriptional activity and decreasing expression of cyclin D1 in both MYCN-amplified and non-amplified cell lines." (PMID 25266063, 2015). "These lines represent MYCN-amplified, NRAS and ALK mutant neuroblastoma subtypes respectively." (PMID 26517508, 2015).
neuroblastoma (continued). "A recent study also showed that non-MYCN amplified neuroblastomas of the unfavorable subset express high levels of MYC instead of MYCN, which appears to be the determining factor of their aggressiveness." (PMID 25017515, 2014). "To examine whether the overexpression of NCYM contributes to the chemosensitivity of neuroblastomas via GSK3β inhibition, we tested the effect of NVP-BEZ235 on the survival of the MYCN/NCYM double transgenic mice." (PMID 24391509, 2014). "Aurora kinase A expression and amplification were shown to be negative prognostic markers in neuroblastoma and to stabilise MYCN." (PMID 25268132, 2014). "In this study, we have found that NCYM is indeed a functional protein that regulates MYCN function in human, but not mouse, neuroblastoma." (PMID 24391509, 2014). "Results of this study have shown that S(+)-ibuprofen destabilized MYCN/MYC in neuroblastoma cell lines with or without MYCN amplification." (PMID 24173829, 2014). "Here, we report that this peptide selectively kills human neuroblastoma cells, especially those with MYCN gene amplification, with much less toxicity to non-malignant human cells." (PMID 24728180, 2014). "Recently, Valentijn and colleagues defined a 157-genes signature that predicts clinical outcome of neuroblastoma irrespective of MYCN amplification." (PMID 24931722, 2014). "First, we examined the dose response of OSU-03012 and VX-680, a potent Aurora kinase inhibitor, on the growth of neuroblastoma cell lines (with and without MYCN amplification)." (PMID 25017515, 2014). "Clinical covariates were used only for the method Cli, including the following attributes: age at diagnosis, MYCN status and INSS stage for neuroblastoma; age, smoking status, gender, stage, and MYC status for lung adenocarcinoma; age, stage, size of tumor, and grade for breast cancer." (PMID 25295525, 2014). "The high-risk group (around 35% survival at 5 years) comprises all cases MYCN-amplified neuroblastoma regardless of stage and age, plus non-MYCN-amplified stage 4 tumors in children ≥18 months old." (PMID 24931722, 2014). "The pathological analysis always found a poorly differentiated or undifferentiated neuroblastoma without MYCN amplification and confirmed the vein tumoral thrombus in the second case." (PMID 25077062, 2014). "The differential intrinsic susceptibility MRI vascular phenotype observed in tumors in the Th-MYCN and Th-ALKF1174L/Th-MYCN models reported herein demonstrates an important role for ALKF1174L in angiogenesis in MYCN-overexpressing neuroblastoma in vivo, strongly suggesting a role in vasculogenesis." (PMID 24667968, 2014). "The cytotoxic effects of metformin against MYCN-nonamplified as well as MYCN-amplified multidrug resistant neuroblastoma cells further signify that metformin can be a promising drug candidate for neuroblastoma therapy." (PMID 25365944, 2014). "Among the subgroup of neuroblastomas without amplification of the MYCN oncogene (n = 40), the TAC combination was correlated with inferior EFS rates (P = 0.037)." (PMID 23533647, 2013). "No major difference in protein levels of p110β levels were detected when comparing stage 4 and stages 1–2 neuroblastomas, although higher levels were seen in MYCN amplified tumors compared to non-amplified tumors (p < 0.05)." (PMID 23597230, 2013). "They purified a protein factor from non-MYCN-amplified neuroblastoma cells culture medium; such a peptide was absent in MYCN-amplified culture medium and exhibited anti-angiogenic properties." (PMID 23482921, 2013). "Expression levels of the miR-17∼92 cluster were measured in 19 MYCN amplified and 8 MYCN non-amplified neuroblastoma cell lines." (PMID 23308108, 2013).